SERPINB3 (serpin family B member 3)
Diseases named in the same sentence as SERPINB3 in open-access papers (continued):
Sharing a sentence is not in itself a finding about the gene and the disease.
psoriasis (22 papers, 2012 to 2025). An autoimmune condition characterized by red, well-delineated plaques with silvery scales that are usually on the extensor surfaces and scalp. "As a molecule elevated in both psoriasis and atopic dermatitis patients, SerpinB3/4 has been shown to cause epidermal barrier dysfunction in experimental mouse models of atopic dermatitis." (PMID 39737188, 2024). "Emerging evidence indicated upregulated SERPINB3/4 expression in serum and KCs of inflammatory skin diseases, including psoriasis and AD, where they regulate inflammatory responses through multiple pathways." (PMID 40995892, 2025). "New evidence has shown that the immune signatures of both Th17 and Th22 were present in the PN lesion, implying that the expression pattern and molecular mechanism of SERPINB3/4 in PN have a common basis with AD and psoriasis." (PMID 40995892, 2025). "Originally found to be highly expressed in multiple tumors, SERPINB3/4 was later found to be elevated in the serum of patients with AD and psoriasis as an inflammatory indicator and was thought to be associated with disease activity in AD and psoriasis." (PMID 40995892, 2025). "Sixteen exosome-related differentially expressed genes (ERDEGs), including CD274 and SERPINB3, are likely to play a significant role in the development of psoriasis." (PMID 40557155, 2025). "In psoriasis, SerpinB3/4 are synthesized by skin fibroblasts and keratinocytes, and then taken up by mast cells to form Pso p27 through cleavage of chymase in mast cells." (PMID 39737188, 2024). "Some DEGs, however, are known to be involved in the pathogenesis of psoriasis (e.g., SERPINB3 and SERPINB4)." (PMID 38892277, 2024). "Several studies have reported increased SerpinB3/B4 expression during inflammatory diseases such as allergic dermatitis, psoriasis, COPD, and asthma, indicating potentially important roles for SerpinB3/B4 in the regulation of inflammatory processes." (PMID 38550710, 2024). "Increased expression of SerpinB3 and B4 have been found in some inflammatory conditions, such as asthma, atopic dermatitis (AD) and psoriasis, and tuberculosis." (PMID 38550710, 2024). "SERPINB3 is highly expressed in psoriasis, cutaneous SCC, and all SCC specimens as well as psoriasis." (PMID 29949603, 2018). "There are inverse correlations between expression of nearby genes and methylation at these sites, including KYNU, OAS2, S100A12, and SERPINB3, whose strong transcriptional upregulation acts as a key indicator of psoriasis." (PMID 26362816, 2015). "The available evidence increasingly indicates that SERPINB3/4 plays a pivotal role in the progression of inflammatory diseases and may serve as a valuable biomarker for atopic dermatitis and psoriasis." (PMID 40995892, 2025). "Comparative analyses between PN, AD and psoriasis could provide insights into the shared and distinct molecular mechanisms of SERPINB3/4 across these conditions." (PMID 40995892, 2025). "Both SerpinB3 and SerpinB13 are highly expressed in psoriasis lesions." (PMID 39737188, 2024). "SERPINB3 is highly expressed in other hyper-proliferative skin disorders, particularly psoriasis." (PMID 32676161, 2020). "The ROC curves demonstrated that the expression levels of eight Hub Genes—POSTN, CD274, CD24, SERPINB3, CXCL13, SMPD3, BIRC5, and RAB27A—exhibited high accuracy (AUC > 0.9) in classifying the Psoriasis and Control groups." (PMID 40557155, 2025). "Elevated levels of the serine protease inhibitors SERPINB3 and SERPINB4 are seen in patients with atopic dermatitis and psoriasis, further clinical studies found that SERPINB4 is closely associated with the clinical severity of these two diseases." (PMID 36999136, 2023). "Nine of the top 50 upregulated DEGs in HS were genes known to be upregulated in psoriasis (PS), including AMPs S100A7, A9, DEFB4, as well as SERPINB3 AND B4." (PMID 30265680, 2018). "Examples of KC-assigned genes strongly elevated in psoriasis lesions included SERPINB4, SPRR2C and SERPINB3." (PMID 24885462, 2014).
psoriasis (continued). "The peripheral immune pattern of PN is similar to that in psoriasis, but distinguished from Th2‐dominated AD, partly accounting for the increased expression of SERPINB3/4 in PN patients with increased nodules not patients with severe pruritus." (PMID 40995892, 2025). "The serpin-derived protein Pso p27, an autoantigen in psoriasis and other chronic inflammatory diseases, is proteolytically derived from SERPINB3 and SERPINB4 through non-canonical cleavage in mast cells by chymase." (PMID 36833193, 2023). "However, the roles of SERPINB3 and SERPINB4 as antigens in psoriasis are controversial and require further investigation, especially SERPINB4, which was highly upregulated in the PE skin." (PMID 35563374, 2022). "Both SERPINB3 and S100A9 are modulators of inflammatory response, highly inducible in keratinocytes, and have been found to be de-regulated in inflammatory skin diseases such as venous ulcers, psoriasis, atopic dermatitis, and skin cancer." (PMID 26318001, 2015). "In addition, the over-accumulation of abnormal SERPINB3 might increase the levels of Pso p27, an autoantigen derived from SERPINB3 and SERPINB4, which is highly involved in the inflammatory process in psoriasis." (PMID 36833193, 2023). "However, whether SerpinB3 is participating in the pathogenesis of psoriasis by itself or by hydrolyzing into Pso p27 has not been investigated." (PMID 39737188, 2024).
lymph node metastasis (14 papers, 2000 to 2025). "In the corresponding non tumoral tissue the expression of SerpinB3 and COX-2, but not that of β-Catenin, was significantly higher in patients with lymph node metastasis, while vascular and perineural invasion did not affect the expression of these molecules." (PMID 28178650, 2017).
liver cancer (13 papers, 2004 to 2024). An epithelial or non-epithelial malignant neoplasm that arises from the liver. "Regarding its role in primary liver cancers, SerpinB3 was found to be expressed in aggressive forms of all these tumors, since its expression is observed in the hepatic stem cell compartment of both fetal and adult cirrhotic livers." (PMID 39061218, 2024). "The aim of this study was to evaluate the ability of SerpinB3 to modulate the Wnt pathway in liver cancer and in monocytic cells, the main type of inflammatory cells in the tumor microenvironment." (PMID 37372056, 2023). "The aim of our study was to evaluate the ability of SerpinB3 to modulate the Wnt pathway in liver cancer and monocytic cells, the main type of inflammatory cells in the tumor microenvironment." (PMID 37372056, 2023). "SerpinB3 expression was highly elevated in primary liver cancer tissues with a high degree of malignancy, and SerpinB3 plays an important role in the upregulation of TGF-β, which mediated EMT and contributes to sorafenib resistance in HCC cells." (PMID 36285158, 2022). "We recently reported that SerpinB3 expression was up-regulated by hypoxia through HIF-2α-dependent mechanisms in human liver cancer cells." (PMID 26634820, 2015). "Here we provide for the first time evidence indicating that Myc expression is significantly and mechanistically up-regulated by SerpinB3 through calpain and Hippo-dependent molecular mechanisms in human liver cancer cells and in a transgenic mice model." (PMID 26634820, 2015). "The study has been designed to investigate and characterize the interplay and functional modulation of Myc by SerpinB3 in liver cancer." (PMID 26634820, 2015). "The present study has been designed to investigate and characterize the interplay and functional modulation of Myc by SerpinB3 in human liver cancer." (PMID 26634820, 2015). "SerpinB3, a serpin over-expressed in injured liver and in primary liver cancer, has been shown to induce apoptosis resistance, epithelial to mesenchymal transition and to increase TGF-beta and Myc expression." (PMID 24517394, 2014). "SERPINB3 is a member of the ovalbumin-serine protease inhibitor family whose expression is upregulated in many advanced cancers with poor prognoses, including breast, lung, ovarian, and liver cancers." (PMID 27167107, 2016). "In the present study, performed on human HCC cell lines and HCC specimens, we report for the first time that SERPINB3 is up-regulated by hypoxic conditions through a selective HIF-2α-dependent mechanism in liver cancer cells and then released in a paracrine way." (PMID 25544768, 2015). "This study has investigated whether SERPINB3 expression is regulated by hypoxia-related mechanisms in liver cancer cells." (PMID 25544768, 2015). "We therefore started to investigate the link between hypoxia and SERPINB3 expression by performing a first series of experiments in which two human liver cancer cell lines (HepG2 and Huh7 cells) were initially exposed to moderate hypoxia (3% O2) for up to 96 hrs." (PMID 25544768, 2015). "These preliminary “in vitro” data may suggest that SERPINB3 up-regulated by hypoxia may have a role in sustaining proliferation and invasiveness of hepatic cancer cells, both effects already reported in previous studies performed using recombinant human SERPINB3 or cells overexpressing SERPINB3." (PMID 25544768, 2015). "SERPINB3 was reported to modulate TGF-beta expression and its high expression indicated poor prognosis in liver cancer." (PMID 36139377, 2022). "Here we provide evidence for the first time indicating that SERPINB3 expression is significantly and mechanistically up-regulated by hypoxia through HIF-2α-dependent mechanisms in human liver cancer cells." (PMID 25544768, 2015).
liver cancer (continued). "Immuno-histochemistry (IHC) and transcript analysis, performed in human HCC specimens, revealed co-localization of the two proteins in liver cancer cells and the existence of a positive correlation between HIF-2α and SERPINB3 transcript levels, respectively." (PMID 25544768, 2015). "SERPINB3 (SB3) is a serine protease inhibitor overexpressed in several malignancies of epithelial origin, including primary liver cancer, where it inhibits apoptosis through poorly defined mechanisms." (PMID 24810714, 2014). "On the basis of these considerations, we have investigated whether SerpinB3 may interact with LRP family members, modulating their cellular expression and functions in liver cancer." (PMID 37372056, 2023). "SERPINB3 has been reported to stimulate proliferation, inhibit apoptosis and, similar to what reported for hypoxia, to trigger epithelial-to-mesenchymal transition (EMT) and increased invasiveness in liver cancer cells." (PMID 25544768, 2015).
atopic dermatitis (8 papers, 2015 to 2025). "SERPINB3 has been implicated in early inflammation and barrier dysfunction in preclinical models of atopic dermatitis and also showed differential expression in GC responders." (PMID 40551926, 2025). "Another notable study done in a mouse model of atopic dermatitis, allergen exposure led to increased expression of Serpinb3a, the mouse homolog of serpin family b member 3 (SERPINB3)/B4." (PMID 40551926, 2025).
lung adenocarcinoma (7 papers, 2012 to 2025). A carcinoma that arises from the lung and is characterized by the presence of malignant glandular epithelial cells. "SERPINB3 or SCCA1 has been investigated in various types of squamous cell carcinoma, but it has only been suggested as a prognostic factor for breast cancer and lung adenocarcinoma." (PMID 23185467, 2012).
melanoma (7 papers, 2015 to 2024). A malignant, usually aggressive tumor composed of atypical, neoplastic melanocytes. "Recently, somatic mutations in SERPINB4 and SERPINB3 (predominantly missense mutations) were described in melanoma, and were associated with improved survival after anti-CTLA4 immunotherapy." (PMID 35085295, 2022). "Another mutational event associated with response to ICIs in melanoma were mutations in SERPINB3 and SERPINB4, which might promote the formation of immunologically significant neoepitopes." (PMID 32969604, 2020). "Along these lines, SerpinB3 was found to be the most significant response-related gene in melanoma treatment with immune checkpoint blockade therapies and has therefore been proposed to be an independent risk factor in melanoma." (PMID 38201652, 2024). "SERPINB3 was the most significant response-related gene in melanoma and mutations in either SERPINB3 or PEG3 can serve as an independent risk factor in melanoma." (PMID 36139377, 2022). "NeoANT-HILL was applied in The Cancer Genome Atlas (TCGA) melanoma dataset and found several putative neoantigens including ones derived from the recurrent RAC1:P29S and SERPINB3:E250K mutations." (PMID 32087727, 2020). "Among 10 newly identified melanoma genes, SERPINB3 is a suicide-substrate protease inhibitor, which balances cell survival and apoptosis, and is shown to be up-regulated in breast, liver, cervical, lung, and other cancers." (PMID 25600636, 2015). "By performing survival analysis based on gene pair mutation, we observed that the mutation of nine gene pairs, such as “SERPINB3|RELN”, “KAT6B|RELN”, and “SERPINB3|PEG3”, were significantly correlated with patient survival in all four independent melanoma datasets (log-rank test p-value < 0.05)." (PMID 36139377, 2022). "Somatic mutations in SERPINB3, a gene encoding a protein of the serpin family of serine protease inhibitors, were reported to predict improved survival from treatment with anti-CTLA4 therapy in two independent cohorts of patients with melanoma." (PMID 34898561, 2021).
asthma (6 papers, 2011 to 2024). "In asthma and AD patients, the induction of SerpinB3 and B4 can be caused by elevated Th2 cytokines IL-4 and IL-13." (PMID 38550710, 2024). "In asthma, the SERPINB3 / B4 complex increases S100A8 production and inflammation by activating P38 / MAPK." (PMID 37422662, 2023). "SERPINB3 has been shown to be upregulated in bronchial epithelial cells from asthma patients by Th2 cytokines IL-4 and IL-13." (PMID 21887273, 2011). "In animal models, deficiency of multiple genes from the IL-13 network can impact on asthma-related traits, including allergic sensitization and/or inflammation (ALOX1551, CYBB52), and airways hyperresponsiveness and mucus production/goblet cell hyperplasia (POSTN53, SERPINB3/454)." (PMID 29367592, 2018).
breast carcinoma (5 papers, 2011 to 2025). "This fact is supported by a previous study in which SERPINB3 expression was found to be associated with poor survival in patients with breast cancer." (PMID 23185467, 2012). "Furthermore, SERPINB3/B4 expression correlates with resistance to platinum combined treatment in NSCLC and poor prognosis of anthracycline-based chemotherapy in breast cancer patients." (PMID 40869249, 2025).
Cirrhosis (5 papers, 2008 to 2024). A chronic disorder of the liver in which liver tissue becomes scarred and is partially replaced by regenerative nodules and fibrotic tissue resulting in loss of liver function. "SerpinB3-IgM complex was positive in 2 out of 17 (12%) patients with chronic hepatitis, in 10 out of 36 (28%) patients with cirrhosis and in 6 out of 26 (23%) patients with HCC." (PMID 22808225, 2012). "In patients with chronic hepatitis the serpinB4-IgM(SCC103)/serpinB3-IgM median ratio was 1.40 (range 1.0–4.5), in patients with cirrhosis it was 1.10 (range 0.9–6.2), and in patients with HCC it was 1.08 (range 0.4–4.2)." (PMID 22808225, 2012). "A trend toward decreasing serpinB4-IgM/serpinB3-IgM median ratio was observed in patients with advanced liver disease, being 1.08 in patients with HCC, 1.10 in patients with cirrhosis and 1.40 in patients with chronic hepatitis (p = 0.079)." (PMID 22808225, 2012).
glioma (5 papers, 2021 to 2026). A benign or malignant brain and spinal cord tumor that arises from glial cells (astrocytes, oligodendrocytes, ependymal cells). "Although SERPINB3 has been implicated in other cancer types, its functional significance in glioma, especially regarding tumor cell invasion, remains poorly defined." (PMID 41550507, 2026). "Our observation of SERPINB3 in the glioma microenvironment now prompts this important new line of investigation." (PMID 41550507, 2026). "Briefly, TMEM44-AS1 is a lncRNA capable of the interaction of SerpinB3 and further increasing the activation of c-Myc signaling in glioma cells." (PMID 34696771, 2021). "In the present study, we showed that TMEM44-AS1 and SerpinB3 mainly interact in the cytoplasm of glioma cells." (PMID 34696771, 2021). "Finally, we performed RNA immunoprecipitation (RIP) assays using specific SerpinB3 antibodies in glioma cells; SerpinB3 was confirmed to interact with TMEM44-AS1." (PMID 34696771, 2021). "Additionally, an immunofluorescence double-labeling experiments assay was performed to identify the subcellular location of TMEM44-AS1 and SerpinB3 in glioma cells." (PMID 34696771, 2021). "Furthermore, knockdown of SerpinB3 in LN-18 and U251 glioma cells reduced Myc and EGR1 expression." (PMID 34696771, 2021). "In gliomas, TMEM44-AS1 binds to SerpinB3 and activates myc and EGR1\IL-6 signaling." (PMID 38040698, 2023). "In accordance, ectopic TMEM44-AS1 increased Myc and EGR1 in both mRNA and protein levels, but not in SerpinB3-knockdown SF26 glioma cells." (PMID 34696771, 2021).
liver disease (5 papers, 2012 to 2025). "SerpinB3 has been previously implicated in the pathogenesis of steatotic liver disease." (PMID 40806209, 2025). "Moreover, SerpinB3 could be used as a potential biomarker for both diagnostic and prognostic purposes, especially in liver disease and cancer." (PMID 39061218, 2024). "This review highlights SerpinB3’s multifaceted roles in liver disease, from fibrosis, carcinogenesis and immune modulation to cell death protection." (PMID 39061218, 2024). "The relevance of SerpinB3 in the progression of liver disease is currently well documented by several clinical studies." (PMID 37238609, 2023). "This review is mainly addressed to analyze the role of SerpinB3 as both a positive and negative molecule, focusing especially on liver disease." (PMID 39061218, 2024).